TSPAN32 (tetraspanin 32)
Synonyms: PHEMX; TSSC6; PHMX
Tractability: Antibody: UniProt predicts a signal peptide or a membrane-spanning region; its Gene Ontology location is reachable by antibodies, with medium confidence.
Gene: Protein-coding gene on chromosome 11 (2,301,990 to 2,318,204, forward strand). Ensembl gene ENSG00000064201.
Subcellular location: Membrane
Subcellular location (Human Protein Atlas): Nucleoplasm
Gene Ontology:
Biological process: cell-cell signaling; regulation of vascular endothelial growth factor signaling pathway; cell communication; signaling
Cellular component: plasma membrane; membrane
Genetic constraint (gnomAD): Loss-of-function variants: 39 observed, 30.83 expected, observed/expected ratio (o/e) 1.26, 90% interval 0.98 to 1.65. The upper end of that interval is the gene's LOEUF score, 1.65, which puts it in group 6 of 6, group 1 being the genes least tolerant of losing a copy. Missense variants: 417 observed, 321.95 expected, observed/expected ratio (o/e) 1.3, 90% interval 1.2 to 1.4. Synonymous variants: 155 observed, 133.42 expected, observed/expected ratio (o/e) 1.16, 90% interval 1.02 to 1.33.
Homologues: Orthologues: chimpanzee TSPAN32 (97% identical), dog TSPAN32 (59% identical), pig TSPAN32 (59% identical), guinea pig TSPAN32 (55% identical), macaque TSPAN32 (55% identical), rat Tspan32 (51% identical), mouse Tspan32 (51% identical), tropical clawed frog tspan32 (24% identical). Paralogues in human: TSPAN11 (17% identical), CD82 (16% identical), CD151 (15% identical), TSPAN4 (15% identical), TSPAN17 (14% identical), TSPAN2 (14% identical), CD63 (14% identical), CD9 (14% identical), TSPAN13 (14% identical), TSPAN9 (14% identical), CD81 (14% identical), TSPAN18 (14% identical), and 20 more.
Diseases named in the same sentence as TSPAN32 in open-access papers:
TSPAN32 is named in the same sentence as 30 diseases in open-access papers, as found by Europe PMC text mining. Sharing a sentence is not in itself a finding about the gene and the disease. The quoted sentences say what the papers report.
autoimmune disease (5 papers, 2019 to 2025). A disorder resulting from loss of function or tissue destruction of an organ or multiple organs, arising from humoral or cellular immune responses of the individual to their own tissue constituents. "TSPAN32 plays a role in controlling immune responses and is implicated in several autoimmune diseases, including multiple sclerosis (MS), Rheumatoid Arthritis (RA) and systemic lupus erythematosus (SLE)." (PMID 40572059, 2025). "Earlier studies have demonstrated that TSPAN32 plays a critical role in maintaining immune homeostasis, and its dysregulation has been associated with altered immune responses and susceptibility to autoimmune diseases and haematopoietic cancer." (PMID 40572059, 2025). "Subsequent studies revealed the involvement of TSPAN32 on different autoimmune disorders, in particular multiple sclerosis (MS) and systemic lupus erythematosus (SLE)." (PMID 39858501, 2025). "These advancements highlight the potential for tetraspanin-targeted therapies, paving the way for similar approaches using TSPAN32 in autoimmune diseases." (PMID 39858501, 2025). "This study follows previous reports on TSPAN32 in immunity and represents a starting point for the ideation of possible new therapies for immunoinflammatory/autoimmune diseases, exploiting its immunoregulatory role in cellular immune responses." (PMID 31487788, 2019). "This is in line with previous studies, showing a role for TSPAN32 in autoimmune disorders." (PMID 39858501, 2025). "Understanding the role of TSPAN32 in immune cell regulation could lead to novel therapeutic strategies for immune-related disorders, including autoimmune diseases, cancer immunotherapy, and infectious diseases." (PMID 39858501, 2025). "Additional studies may also be warranted to dismantle whether defective expression of TSPAN32 is also observed in other T cell-mediated autoimmune diseases." (PMID 31963428, 2020). "Overall, these data suggest an immunoregulatory role for TSPAN32 in T helper immune response and may represent a target of future immunoregulatory therapies for T cell-mediated autoimmune diseases." (PMID 31487788, 2019). "In addition, genetic studies provide compelling evidence linking TSPAN32 to autoimmune diseases." (PMID 39858501, 2025).
Autoimmunity (3 papers, 2019 to 2025). The occurrence of an immune reaction against the organism's own cells or tissues. "Genome-wide association studies (GWASs) have implicated TSPAN32 SNPs in autoimmunity." (PMID 39858501, 2025). "The unique property of TSPAN32 of regulating the immune responses offers the possibility to develop novel therapeutic opportunities for autoimmune disorders." (PMID 34207245, 2021). "The disruption of the control switch provided by TSPAN32 may be one of the possible promoters of the inflammatory damage to myelin, offering not only an important insight into the pathogenesis of MS, but also novel therapeutic targets that may underlie potential primary drivers of autoimmunity." (PMID 31487788, 2019). "We may speculate that the alteration of the control provided by TSPAN32 could represent a possible promoter of the inflammatory damage occurring in immunoinflammatory diseases, such as SLE, and hence, a newly discovered driver of autoimmunity." (PMID 34207245, 2021).
experimental autoimmune encephalomyelitis (3 papers, 2019 to 2021). An autoimmune demyelinating disease of the central nervous system that is produced experimentally in animals by the injection of homogenized brain or spinal cord in Freund's adjuvant. "Encephalitogenic T cells from Myelin Oligodendrocyte Glycoprotein (MOG)-Induced Experimental Autoimmune Encephalomyelitis (EAE) mice showed significantly lower levels of TSPAN32 and increased levels of CD9, CD53, CD82 and CD151." (PMID 31487788, 2019). "The expression of TSPAN32 was assessed in CD4+ T cells from a model of experimental autoimmune encephalomyelitis (EAE)." (PMID 31487788, 2019). "Moreover, significantly lower levels of TSPAN32 were found in encephalitogenic T cells from myelin oligodendrocyte glycoprotein (MOG)-Induced experimental autoimmune encephalomyelitis (EAE) mice." (PMID 31963428, 2020).
multiple sclerosis (3 papers, 2019 to 2023). A progressive autoimmune disorder affecting the central nervous system resulting in demyelination. "In the present study, by making use of ex vivo and in silico analysis, we aimed to better characterize the pathophysiological and diagnostic/prognostic role of TSPAN32 in T cell immunity and in multiple sclerosis (MS)." (PMID 31963428, 2020). "In the present work, we have characterized the modulation of TSPAN32 in T cell-mediated immune responses and in multiple sclerosis by means of in silico, in vitro and ex vivo analysis." (PMID 31487788, 2019). "Finally, we have investigated the role of TSPAN32 in multiple sclerosis." (PMID 31487788, 2019).
B-cell chronic lymphocytic leukemia (2 papers, 2021 to 2025). "Although our data on the effect of BAFF comes only from murine B cells and primary human B cell chronic lymphocytic leukemia samples, nevertheless, we can observe a consistent reduction of TSPAN32 expression upon BAFF exposure." (PMID 34207245, 2021). "Importantly, our results indicate that TSPAN32 downregulation is not restricted to T-ALL, as reduced expression was also observed in B-ALL and chronic lymphocytic leukemia (CLL), highlighting a broader pattern of suppression that transcends specific lymphoid lineages." (PMID 41007654, 2025).
Burkitt lymphoma (2 papers, 2025). A rare form of malignant mature B-cell non-Hodgkin lymphoma. "TSPAN32 expression is significantly downregulated in endemic, sporadic, and HIV‐associated Burkitt Lymphoma, and it is regulated by the TF3/ID3 pathway." (PMID 40572059, 2025).
inflammatory bowel disease (2 papers, 2025). A spectrum of small and large bowel inflammatory diseases of unknown etiology. "Genome‐wide studies have also associated TSPAN32 variants with other autoimmune conditions such as inflammatory bowel disease (IBD) and systemic sclerosis (SSc), emphasising its role in immune system regulation." (PMID 40572059, 2025).
leukemia (2 papers, 2023 to 2025). A malignant (clonal) hematologic disorder, involving hematopoietic stem cells and characterized by the presence of primitive or atypical myeloid or lymphoid cells in the bone marrow and the blood. "We demonstrate that TSPAN32 is broadly downregulated in these leukemias and inversely correlates with cell cycle gene expression, supporting a model in which TSPAN32 acts as a quiescence-promoting factor whose silencing facilitates oncogenic proliferation." (PMID 41007654, 2025). "Collectively, these results indicate that restoring TSPAN32 expression restrained Ph+ leukemia cell proliferation and promoted cell sensitivity to Imatinib." (PMID 36854750, 2023). "Conversely, the use of shRNA to knockdown TSPAN32 in Ph+ leukemia cells, made leukemia cells less sensitive to Imatinib." (PMID 36854750, 2023). "In this study, we identified TSPAN32 as a tumor suppressor gene in Ph+ leukemias, whose expression was decreased by BCR-ABL." (PMID 36854750, 2023). "We observed that TSPAN32 overexpression in leukemia cells resulted in increased sensitivity to imatinib." (PMID 36854750, 2023). "High expression of Tspan32 prevented leukemia progression and inhibited leukemia cell infiltration into peripheral organs, including the spleen and lung." (PMID 36854750, 2023). "Post-transcriptional mechanisms—such as microRNA–mediated silencing—could also contribute to low TSPAN32 levels in leukemia." (PMID 41007654, 2025). "Comprehensive profiling of TSPAN32 expression across genetically annotated patient cohorts will be necessary to delineate the precise relationship between leukemia subtype, underlying mutations (e.g., NOTCH1, FBXW7, PHF6, HOXA cluster abnormalities), and TSPAN32 regulation." (PMID 41007654, 2025). "Moreover, confirming the direct binding of TAL1 isoforms and NOTCH1 effectors to TSPAN32 regulatory elements, as well as determining the functional impact of TSPAN32 reactivation on leukemia cell behavior, will be critical next steps." (PMID 41007654, 2025). "This variability highlights the complexity of transcriptional regulation in leukemia and the possibility that TSPAN32 expression may be preserved in certain molecular subtypes or disease contexts." (PMID 41007654, 2025). "The ectopic expression of TSPAN32 inhibited the proliferation of these Ph+ leukemia cells." (PMID 36854750, 2023). "Tspan32 overexpression significantly prevented BCR-ABL induced leukemia progression in a murine model and impaired leukemia stem cell (LSC) proliferation." (PMID 36854750, 2023). "Nonetheless, it is critical to note that not all leukemia samples exhibited lower TSPAN32 expression relative to healthy controls, suggesting that TSPAN32 repression is neither universal nor attributable to a single pathogenic mechanism." (PMID 41007654, 2025).
lymphoma (2 papers, 2025). A malignant (clonal) proliferation of B- lymphocytes or T- lymphocytes which involves the lymph nodes, bone marrow and/or extranodal sites. "Future studies should focus on elucidating the precise molecular mechanisms through which TSPAN32 contributes to B cell development and BL pathogenesis, as well as the therapeutic potential of targeting TSPAN32 dysregulation in these types of lymphomas." (PMID 40572059, 2025). "By examining the transcriptional mechanisms underlying TSPAN32 dysregulation across endemic, sporadic, and HIV‐associated BL subtypes, we seek to identify its role in lymphoma pathogenesis." (PMID 40572059, 2025). "Using exome sequencing, they identified six recurrent, rare, and potentially deleterious variants within 5 kb of lymphoma-associated GWAS loci in 75 MM cases (BTNL2, EOMES, TNFRSF13B, IRF8, ACOXL, TSPAN32)." (PMID 41300981, 2025).
systemic sclerosis (2 papers, 2025). A chronic disorder, possibly autoimmune, marked by excessive production of collagen which results in hardening and thickening of body tissues. "Another GWAS meta-analysis on systemic sclerosis (SSc) found SNP rs2651804 near TSPAN32 strongly associated with SSc, particularly the limited cutaneous subtype." (PMID 39858501, 2025).
Bovine mastitis (1 paper, 2023). INFLAMMATION of the UDDER in cows. "For many of the genes that overlapped with dMHB discriminant signatures in this study, such as ZNF691, MAML2, ZC2H7B, CD101, TSPAN32, and MAML2, this is the first report of their involvement in bovine mastitis." (PMID 37373515, 2023).
glomerular disease (1 paper, 2017). "The down regulation of Scx and Tspan32 genes however occurred in Cd151−/− glomeruli of both strains of mice indicating that it is an effect of Cd151 absence regardless of glomerular disease susceptibility." (PMID 29167507, 2017).
metastatic tumor (1 paper, 2024). "The downregulation of CD63 and TSPAN32 in immune cells within metastatic tumor suggests a potential reduction in immune cell activation and responsiveness." (PMID 38255741, 2024). "Downregulation of CD63 and TSPAN32 in immune cells within the metastatic tumor may be related to reduced immune cell activation and responsiveness." (PMID 38255741, 2024).
primary progressive MS (1 paper, 2020). "In a similar manner, the expression profile of TSPAN32 in secondary progressive and primary progressive MS seems of interest." (PMID 31963428, 2020).
relapsing (1 paper, 2020). "A significant reduction in TSPAN32 expression was observed in PBMCs from MS patients in both stable and relapsing disease (p < 0.001)." (PMID 31963428, 2020).
type 2 diabetes (1 paper, 2025). "Only seven genes had the same direction of effect for comparison of type 2 diabetes samples and healthy samples in all eight datasets: LOC112268118 and MPO had positive logFC, and IL18BP, DELE1, TSPAN32, ITFG2, and NISCH all had negative logFC." (PMID 41465472, 2025).
Wilms tumor (1 paper, 2021). An embryonal neoplasm characterized by the presence of epithelial, mesenchymal, and blastema components. "TSPAN32 has been found as a potential tumor suppressor in Wilms tumors, while the expression was higher in tumor samples compared to normal tissues in our study." (PMID 34540825, 2021).
tumor (9 papers, 2015 to 2025). "The downregulation of TSPAN32 across BL subtypes suggests its potential role as a tumour suppressor gene." (PMID 40572059, 2025). "Ectopic expression of TSPAN32 in Ph+ cell lines inhibited cellular viability and increased the anti-tumor effects of Imatinib." (PMID 36854750, 2023). "Given the limited success of GSIs as monotherapies due to toxicity and resistance, combining them with approaches that upregulate tumor-suppressive genes like TSPAN32 may provide a rational path toward improved treatment strategies." (PMID 41007654, 2025). "TSPAN32 may act as a tumour suppressor, with its downregulation contributing to uncontrolled proliferation." (PMID 40572059, 2025). "In addition, TSPAN32 is a member of the tetraspanins, which contribute to tumor growth through angiogenesis, immunological function, platelet coagulation, and infection." (PMID 36980682, 2023). "Tetraspanin 32 (TSPAN32), a member of the tetraspanin superfamily, is one of several tumor-suppressing subtransferable fragments located in the imprinted gene domain of chromosome 11p15.5, a critical tumor-suppressor gene region." (PMID 39858501, 2025). "Additionally, transcriptome profiling following TSPAN32 restoration could reveal downstream targets involved in cell cycle arrest, metabolic reprogramming, or immune signaling, thereby clarifying the mechanistic basis of its potential tumor-suppressive function." (PMID 41007654, 2025). "A positive association between alcohol intake and methylation in the DMR.A79 was related to the TSPAN32 (tetraspanin 32) gene, also known as the TSSC6 gene, which is one of the several tumor suppressor genes located at locus 11p15.5 in the imprinted gene domain of chromosome 11." (PMID 30940212, 2019).
cancer (5 papers, 2015 to 2025). A tumor composed of atypical neoplastic, often pleomorphic cells that invade other tissues. "Dysregulation of these processes is a hallmark of cancer, and the involvement of TSPAN32 in these pathways underscores its potential role in suppressing malignant transformation." (PMID 40572059, 2025). "Targeting TSPAN32 or its associated pathways may offer new avenues for modulating immune responses and enhancing immune surveillance against pathogens or cancer cells." (PMID 39858501, 2025). "By elucidating the complex interplay between TSPAN32 and immune cell biology, this study opens new avenues for therapeutic interventions targeting TSPAN32 in immune-related diseases, cancer immunotherapy, and hematological disorders." (PMID 39858501, 2025). "TSPAN32 and C11orf21, both located in the 11p15.5 imprinted region on chromosome 11, play key roles in haematopoietic regulation and cancer." (PMID 41421321, 2025). "CASP8 and H19 have been previously associated with WTs, and H19 in particular has been associated with sporadic bilateral disease, whereas RB1, Mir-195 and TSPAN32 aberrations have not previously been identified in WTs, although detected in other cancers." (PMID 25763109, 2015).
hematologic malignancies (2 papers, 2025). "By integrating gene expression patterns, regulatory networks, and functional associations, we establish a framework for future research to explore the therapeutic potential of targeting TSPAN32 in immune-related and hematological disorders." (PMID 39858501, 2025).
TSPAN32 also shares sentences with these, for which no sentence is quoted: systemic lupus erythematosus (4 papers); chronic myeloid leukemia (3); haematopoietic cancer (2); acute lymphoblastic leukemia (1); B-cell acute lymphoblastic leukemia (1); infection (1); infectious disease (1); lung adenocarcinoma (1); rheumatoid arthritis (1); T-cell leukemia (1).